BIRC5 (baculoviral IAP repeat containing 5)
Diseases named in the same sentence as BIRC5 in open-access papers (continued):
Sharing a sentence is not in itself a finding about the gene and the disease.
glioblastoma (20 papers, 2016 to 2025). The most malignant astrocytic tumor (WHO grade IV). "Overall, the RUNX1-PIF1/BIRC5-p21 pathway was considered to cause apoptosis and cell cycle arrest for some cells in glioblastoma." (PMID 36085167, 2022). "Recently, the peptide-conjugate vaccine SurVaxM, which targets the survivin (BIRC5) tumor antigen, has shown promise in the treatment of newly diagnosed glioblastoma (nGBM)." (PMID 41066027, 2025). "The downregulation of BIRC5 likely reduces tumor burden in glioblastoma-expressing mice and humans through microtubule destabilization in interphase and mitosis, thereby facilitating apoptosis in rapidly dividing cancer cells." (PMID 40422257, 2025). "In summary, we found that RUNX1 regulates the expression of BIRC5, which is involved in the induction of apoptosis in glioblastoma." (PMID 36085167, 2022). "Brd4 inhibition abrogated an the constitutively active mutant form of the EGFR receptor (EGFRvIII)-induced transcription expression of BIRC5 and eliminated IL-6-mediated therapy resistance in glioblastoma." (PMID 36539410, 2022). "A previous study showed that Dnmt1, Dnmt3a, and Dnmt3b can regulate the methylation status of BIRC5 in glioblastoma multiforme." (PMID 35664300, 2022). "Furthermore, inorganic iron oxide NPs carrying therapeutic siRNAs were efficiently used for tracking siRNA-based gene therapy targeting the BCL2 and BIRC5 of oral cancer and glioblastoma cells." (PMID 35564123, 2022). "We hypothesised that RUNX1 regulates p21 and BIRC5 for some cells in glioblastoma and is involved in tumour growth." (PMID 36085167, 2022). "Here, we show that RUNX1 downregulates p21 by enhancing expressions of BIRC5 and PIF1, conferring anti-apoptotic properties on glioblastoma." (PMID 36085167, 2022). "A PTV-loaded nanocarrier was developed to trigger the apoptosis of glioblastoma multiforme cells by reducing the mRNA levels of NFKB, IL6, BIRC1, and BIRC5." (PMID 34925455, 2021). "In the main signaling pathways, Wnt/β-Catenin, TGFβ, PI3K/Akt, ERK, CXCR4, BIRC5, CTNNB1, FZD4, HGF, EGFR, and other proteins enhance the expression of EMT markers and promote the migration and proliferation of glioblastoma." (PMID 32154177, 2020). "In summary, we have described a branched multipeptide vaccine capable of stimulating a response to multiple CD8+ T cell epitopes from glioblastoma-TAAs such as ERBB2, BIRC5 and CD99." (PMID 27409668, 2016). "In the present study, we designed a peptide immunotherapy for glioblastoma using ERBB2, BIRC5 and CD99 peptides as TAAs." (PMID 27409668, 2016). "In the present study, we investigated the possibility of using peptide immunotherapy for glioblastoma by using ERBB2-, BIRC5- and CD99-specific CTLs generated by multipeptide-pulsed DCs." (PMID 27409668, 2016). "Branched multipeptides from ERBB2, BIRC5, and CD99 stably bound with T2 cells, and multipeptide-pulsed denditric cells–cytotoxic T lymphocytes exhibited remarkable cytotoxic activity against primary glioblastoma cells." (PMID 29534016, 2018). "Moreover, they found new evidence that YAP/TAZ can abnormally activate the target gene, BIRC5, accompanied with down-regulation of LATS1/2, in turn simulating aberrant cell growth and neoplasia in glioblastoma." (PMID 29896440, 2018). "Furthermore, p21 expression was also upregulated in cells in which BIRC5, downstream of RUNX1, was K/D, suggesting that p21 was not directly regulated by RUNX1, but may be regulated via BIRC5 in glioblastoma." (PMID 36085167, 2022). "In our previous study, we detected positive expression of v-erb-b2 erythroblastic leukemia viral oncogene homolog-2 (ERBB2), baculoviral IAP repeat containing-5 (BIRC5) and the glycoprotein CD99 in most glioblastoma tissues, and negative expression in normal brain tissues." (PMID 27409668, 2016).
endometrial cancer (17 papers, 2008 to 2024). Primary or metastatic malignant neoplasm involving the endometrium (mucous membrane that lines the endometrial cavity). "The BIRC5 promoter is unmethylated in normal endometrial tissue, but methylation levels increase from low to high grade endometrial cancer and correlate with increased survivin protein expression." (PMID 39687493, 2024). "Within this network, 100 DEGs were found, and three genes (BIRC5, CENPF, HJURP) overlapping with DEM targets were associated with worse overall survival in endometrial cancer." (PMID 39108650, 2024). "It was found that BIRC5 acts to promote endometrial carcinoma progression and is overexpressed in both endometrial carcinoma and endometrial carcinoma cell lines." (PMID 35672846, 2022). "Using multivariate COX regression analysis, two genes associated with endometrial carcinoma prognosis—PIM1 and BIRC5 were obtained, both of which were high-risk genes." (PMID 35672846, 2022). "Four ARGs (CDKN2A, PTK6, ERBB2 and BIRC5) were selected to establish a prognostic model of endometrial cancer." (PMID 33109128, 2020). "Immunohistochemistry suggested that among the four ARGs the protein levels of CDKN2A, PTK6, ERBB2, and BIRC5 were higher in endometrial cancer than healthy endometrial tissue." (PMID 33109128, 2020). "In summary, by collecting and analyzing the transcript information of endometrial cancer samples from TCGA database, we identified four prognosis-associated autophagy genes (CDKN2A, PTK6, ERBB2, and BIRC5)." (PMID 33109128, 2020). "Our prognostic model assessing four ARGs (CDKN2A, PTK6, ERBB2, and BIRC5) suggested their potential as independent predictive biomarkers and therapeutic targets for endometrial cancer." (PMID 33109128, 2020). "We constructed a prognostic model of endometrial cancer containing four risk ARGs (CDKN2A, PTK6, ERBB2, and BIRC5) using multivariate and univariate Cox, and LASSO regression analyses." (PMID 33109128, 2020). "For example, the baculoviral IAP repeat containing 5(BIRC5) gene, which codes for the Survivin protein involved in both apoptosis and cell cycle regulation, has been found to be highly methylated in endometrial cancer samples, yet its high expression is correlated with hypermethylation." (PMID 38711158, 2024). "Similarly, high expression of BIRC5 was an independent prognostic factor for overall survival in clear-cell renal cell carcinoma and endometrial cancer." (PMID 35309512, 2022). "This demonstrates that BIRC5, besides serving as an independent prognostic factor, may also serve as a new treatment target for endometrial carcinoma." (PMID 35672846, 2022). "In the present study, we found that BIRC5 was significantly overexpressed in endometrial cancer and an independent prognostic factor, suggesting that BIRC5 might promote endometrial cancer by inhibiting autophagy in cancer cells." (PMID 33109128, 2020). "Moreover, knockdown of BIRC5 in endometrial cancer cell lines induced cell apoptosis, which indicated that BIRC5 is not only a prognostic factor also a promising therapeutic target for endometrial cancer." (PMID 31781484, 2019). "In addition, the data also shows that the higher expression of AKT1, GTSE1, BIRC5, AURKA, and KNSTRN is significantly associate with poor prognosis of endometrial cancer." (PMID 31781484, 2019). "Moreover, the data also shows that the higher expression of AKT1, GTSE1, BIRC5, AURKA, and KNSTRN is significantly associate with poor prognosis of endometrial cancer." (PMID 31781484, 2019). "As shown in the endometrial cancer pathway (hsa05213), both BAX and BIRC5 are Astragalus membranaceus targets that can inhibit tumour proliferation." (PMID 34513331, 2021). "We selected the six hub genes (GTSE1, BIRC5, AURKA, PBK, KNSTRN, and PSMB10) and AKT1 to evaluate gene expression values in endometrial cancer using IHC." (PMID 31781484, 2019).
endometrial cancer (continued). "To further confirm these results, we compared the expression of PIM1 and BIRC5 genes in the control and drug groups by q-PCR, and the mRNA levels of both PIM1 and BIRC5 were significantly reduced in 25uM puerarin compared to the control endometrial cancer cells." (PMID 35672846, 2022).
renal cell carcinoma (16 papers, 2015 to 2023). "Two studies have reported associations with RCC in Chinese population showing polymorphism in the promoter of the BIRC5 gene and variation in the XRCC6 locus, to be the susceptibility candidates for renal cell carcinoma." (PMID 25945350, 2015). "According to CTRP drug sensitivity analysis, high level of CBX2, BLNK, PLK4, STIL and BIRC5 were associated with increased sensitivity to inhibitors of VEGF and MET pathways, which happened to be two crucial driver pathways of renal cell carcinoma." (PMID 37917664, 2023). "MALAT1 reduces the expression of miR-203 to promote the expression of BIRC5 and accelerate the occurrence and development of renal cell carcinoma." (PMID 34193046, 2021). "In conclusion, MALAT1 accelerates the development and progression of renal cell carcinoma by decreasing the expression of miR‐203 and promoting the expression of BIRC5." (PMID 31250518, 2019). "BIRC5 overexpression has been reported in various malignancies, and it was a prognostic marker in renal cell carcinoma." (PMID 31422942, 2019). "The immune-related genes BIRC5, INHBE, and IL20RB were upregulated in a TMBhigh group and were associated with a poor prognosis, and a combination of PD-1 and CTLA-4 blockers was suggested for the treatment of advanced renal cell carcinoma with aberrations." (PMID 34795663, 2021). "In addition, in renal cell carcinoma, MALAT1 can regulate the miR‐203/BIRC5 axis to accelerate tumor progression." (PMID 34240756, 2021).
leukemia (15 papers, 2015 to 2026). A malignant (clonal) hematologic disorder, involving hematopoietic stem cells and characterized by the presence of primitive or atypical myeloid or lymphoid cells in the bone marrow and the blood. "We aimed to explore the enormous potential of this system in generating knockout in human leukemia cells in culture and to elucidate the BIRC5 mutation impact on cellular function." (PMID 31104397, 2019). "We utilized human leukemia cells to test the dasatinib-DNA Au-NPs in a more complex cellular environment as high BIRC5 mRNA expression and dasatinib-sensitive mutations or kinase dependence frequently occur in both chronic and acute leukemia." (PMID 27203672, 2016). "Of those with active leukemia, 67% (6/9) were positive for BIRC5, 33% (3/9) for WT1, and 22% (2/9) for PRAME." (PMID 36248870, 2022). "ICG-001 induced the reduction of self-renewal capacity of B-ALL cells, through downregulation of survivin (the product of BIRC5 gene), thus overcoming drug-resistance in primary leukemia cells." (PMID 33255367, 2020). "A previous study has clarified that BIRC5 gene is overexpressed in numerous malignancies such as leukemia and correlated with tumor progression and drug resistance." (PMID 31104397, 2019). "We also verify and confirm that BIRC5 oncogene is a promising new avenue in the treatment of cancers, such as leukemia." (PMID 31104397, 2019). "Following confirmation of efficient uptake of Au-NPs into leukemia cells, we tested dasatinib-DNA Au-NPs with K562 leukemia cells that express BIRC5 mRNA, harbor a dasatinib-sensitive BCR/ABL translocation, and exhibit high SRC kinase activity." (PMID 27203672, 2016). "We also tested dasatinib-DNA Au-NPs with the Kasumi-1 leukemia cell line that harbors an activating KIT mutation and expresses BIRC5 mRNA." (PMID 27203672, 2016). "Except for Leukemia, BIRC5 mRNA was highly expressed in all tumor tissues." (PMID 33431968, 2021). "Alternatively genetically modified TCRs could be used to target BIRC5 expressing cancer cells, especially because of its wide overexpression in a number of tumour types including leukaemia and with regard to this study AML." (PMID 34638823, 2021). "In addition, FLT3 inhibitors have been shown to cause anti-proliferative activity, in leukaemia cell lines with FLT3-ITD, through the downregulation of MCL-1 and BIRC5, the latter via the STAT3/5 pathway." (PMID 34638823, 2021). "To determine if these tumor antigens could be simultaneously detected and discriminated for quantitation, we used cancer cell lines known to express the three TAA: hepatoblastoma (HEP3B), which expresses BIRC5; and K562, an immortalized leukemia line that expresses WT1 and PRAME." (PMID 36248870, 2022). "Furthermore, these findings corroborate the induction of cellular stress and pro-apoptotic activity in cells of healthy origin when exposed to EMF at mT magnitude, and for the first time indicate a potential mechanistic link to EMF-related reports on leukemia through elevated expression of BIRC5." (PMID 34574442, 2021). "Perhaps our data already constitute a potential mechanistic explanation to reports on increased childhood leukemia upon residential EMF exposure, as BIRC5 promotes cell proliferation and constitutes an important biomarker to predict the clinical outcome in AML patients." (PMID 34574442, 2021). "To determine whether BIRC5 suppression by the CRISPR/Cas9n editing system is sufficient to induce a change in cell fate, we applied this system to the leukemia cell lines, KG-1 and HL-60." (PMID 31104397, 2019). "Dasatinib-DNA Au-NPs targeting the human BIRC5 mRNA, but not a scrambled control, significantly inhibit the proliferation of dasatinib-sensitive leukemia cell lines." (PMID 27203672, 2016). "Of the 19 patients with active disease, including those leukemias without elevated TAA/ABL1, the blood levels of WT1/ABL1, PRAME/ABL1, and BIRC5/ABL1 exceeded healthy donors (p<0.0001, p=0.0286, and p=0.0064 respectively)." (PMID 36248870, 2022).
leukemia (continued). "ddPCR simultaneously quantitated mRNA expression of WT1, PRAME, BIRC5, and ABL1 and the TAA/ABL1 blood ratio was measured in patients with and without active leukemia after HCT." (PMID 36248870, 2022).
triple-negative breast carcinoma (13 papers, 2012 to 2022). An invasive breast carcinoma which is negative for expression of estrogen receptor (ER), progesterone receptor (PR), and human epidermal growth factor receptor 2 (HER2). "Down-regulation of BIRC5 decreased the proliferation of triple-negative breast cancer cells, implying that BIRC5 acts as a tumor driver." (PMID 35178302, 2022). "Markers for cell proliferation like Top2a, Birc5, and Mki67 are highly expressed, so are markers for metastasis like Msln, Ect2, and Plk1, which are known to be overexpressed in triple-negative breast cancer (TNBC)." (PMID 32793490, 2020). "BIRC5 siRNA significantly inhibited cell proliferation in triple-negative breast cancer cells." (PMID 29190974, 2017). "Birc5 is also downstream of STAT3 transcription activity in triple-negative breast cancer, and STAT3 binding to the Birc5 promoter has been demonstrated through ChIP analysis." (PMID 33557010, 2021). "Our results also demonstrated strongly higher BIRC5 expression in basal-like and triple-negative breast cancer patients with respect to non-basal-like and non-triple-negative patients." (PMID 32043523, 2020).
cervical cancer (12 papers, 2017 to 2025). A primary or metastatic malignant neoplasm involving the cervix. "Specifically with a DTX regimen, depletion of survivin (encoded by BIRC5) was reported in cervical cancer cells responding to the taxane treatment." (PMID 40385549, 2025). "Inhibition of BIRC5 improves cervical cancer cell sensitivity to radiotherapy." (PMID 34691238, 2021). "Additionally, circulating IgG antibodies generated from BIRC5 may be used as a biomarker for the early detection of cervical cancer and malignant gliomas." (PMID 36358602, 2022). "In addition, circulating IgG antibodies derived from BIRC5 could serve as a biomarker for malignant glial tumor and early diagnosis of cervical cancer." (PMID 31093306, 2019). "Anti-BIRC5 IgG could serve as a biomarker for the early diagnosis of cervical cancer." (PMID 29190974, 2017). "This research highlights BIRC5, HOXA1, and RARB as significant therapeutic targets in cervical cancer due to their critical involvement in its development." (PMID 40564176, 2025). "Through this analysis, certain genes, including BIRC5 (survivin), HOXA1, and RARB, were identified as highly relevant in cervical cancer due to their topological properties and high scores in databases like Genecards." (PMID 40564176, 2025). "In another study, the miRNAs, miR-203 and miR-30b and the target genes BIRC5, HOXA1, and RARB were suggested to be critical players in the pathogenesis of cervical cancer, as revealed by the systematic analysis of dysregulated miRNAs and their targets in cervical cancer." (PMID 30020984, 2018).
colon carcinoma (11 papers, 2014 to 2025). "Proteomic analyses conducted during research studies confirmed that mushroom extracts reduced BIRC5 levels in colon cancer cell lines." (PMID 40508113, 2025). "Overall, downregulation of BIRC5 inhibits the colon cancer survival rate through inducing programmed cell death, restricting cancer cell proliferation, and enhancing chemo sensitivity." (PMID 40508113, 2025). "CNVs specific for MSS colon cancer IntOMICS identified edges from CNV to associated GE in five out of six genes of interest: KRAS, MYC, BIRC5, RAC3, and SMAD4." (PMID 35996085, 2022). "And increased expression of BIRC5 is related to poor clinical outcome in patients with colon cancer patients." (PMID 30186855, 2018). "Overexpression of BIRC5 may show relationships with various types of cancer, particularly human colon cancer." (PMID 40508113, 2025). "Studies showed that BIRC5 expression is significantly increased in lung, breast, and colon cancers." (PMID 35880695, 2023). "It is found that BIRC5 is highly expressed in colon cancer cell lines." (PMID 30186855, 2018). "However, no WWOX-induced changes were observed in the transcription of apoptosis-related genes (BAX, BCL2, BIRC5), whose expression was observed to correlate with WWOX in colon tumour specimens and other cancer tissues." (PMID 24938873, 2014).
bladder cancer (10 papers, 2014 to 2026). "Survivin (encoded by the gene BIRC5) plays an important role in the carcinogenesis of bladder cancer." (PMID 27978829, 2016). "MiR-138-5p also suppresses the growth and invasiveness of bladder cancer via the downregulation of BIRC5 expression." (PMID 39596660, 2024). "We demonstrated that BIRC5 repression by miR-138-5p suppressed the proliferative and invasive characteristics of bladder cancer cells and that miR-138-5p exerted an anti-tumor effect by negatively regulating BIRC5 in a xenograft mouse model." (PMID 27978829, 2016). "Taken together, our findings provide the first clues regarding the role of miR-138-5p as a tumor suppressor in bladder cancer by inhibiting BIRC5 translation." (PMID 27978829, 2016). "Similarly, IGF2BP3 recognizes the m6A signal added by METTL3 in the 3′ UTR of BIRC5 mRNA to stabilize it, resulting in cell growth and metastasis of bladder cancer." (PMID 37554271, 2023). "Because microRNAs are powerful post-transcriptional regulators of gene expression, we used bioinformatic analyses to search for microRNAs that could potentially target BIRC5 in the setting of bladder cancer." (PMID 27978829, 2016).